BFSP1 (beaded filament structural protein 1)
Description:
Required for the correct formation of lens intermediate filaments as part of a complex composed of BFSP1, BFSP2 and CRYAA. Involved in altering the calcium regulation of MIP water permeability.
Synonyms: CP115; LIFL-H; CP94; filensin; CTRCT33
Tractability: Antibody: UniProt places it where antibodies can reach, with medium confidence; its Gene Ontology location is reachable by antibodies, with medium confidence; the Human Protein Atlas places it where antibodies can reach.
Gene: Protein-coding gene on chromosome 20 (17,493,905 to 17,569,220, reverse strand). Ensembl gene ENSG00000125864.
Subcellular location: Cell membrane; Cytoplasm; Cytoplasm, cytoskeleton; Cytoplasm, cell cortex
Subcellular location (Human Protein Atlas): Cytosol; Plasma membrane
Gene Ontology:
Molecular function: protein binding; structural constituent of cytoskeleton; structural constituent of eye lens; structural molecule activity
Biological process: intermediate filament organization; lens fiber cell development; cytoskeleton organization
Cellular component: cytosol; plasma membrane; cytoplasm; intermediate filament; cell cortex; cytoskeleton
Genetic constraint (gnomAD): Loss-of-function variants: 40 observed, 37.97 expected, observed/expected ratio (o/e) 1.05, 90% interval 0.82 to 1.37. The upper end of that interval is the gene's LOEUF score, 1.37, which puts it in group 5 of 6, group 1 being the genes least tolerant of losing a copy. Missense variants: 850 observed, 791.36 expected, observed/expected ratio (o/e) 1.07, 90% interval 1.01 to 1.14. Synonymous variants: 352 observed, 318.06 expected, observed/expected ratio (o/e) 1.11, 90% interval 1.01 to 1.21.
Homologues: Orthologues: chimpanzee BFSP1 (99% identical), macaque BFSP1 (95% identical), pig BFSP1 (71% identical), rat Bfsp1 (68% identical), mouse Bfsp1 (67% identical), guinea pig BFSP1 (66% identical), dog BFSP1 (65% identical), rabbit BFSP1 (62% identical), tropical clawed frog bfsp1 (43% identical), zebrafish bfsp1 (27% identical).